NSD1 (nuclear receptor binding SET domain protein 1)
Diseases named in the same sentence as NSD1 in open-access papers (continued):
Sharing a sentence is not in itself a finding about the gene and the disease.
neuroblastoma (18 papers, 2007 to 2023). Neuroblastoma (NB) is the most common solid, extracranial childhood tumor. "For example, hypermethylation mediated by NSD1 is related to a poor prognosis in patients with high-risk neuroblastoma." (PMID 35200072, 2022). "Epigenetic silencing of NSD1, through promoter hypermethylation, has been associated with neuroblastoma and gliomas." (PMID 36230787, 2022). "In neuroblastomas and gliomas, NSD1 promoter methylation-associated gene silencing predicts worse survival." (PMID 31321084, 2019). "The somatic mutations in NSD1 have been identified in multiple myelomas, lung cancer, neuroblastomas and glioblastomas." (PMID 27187383, 2016). "In the large series of Tatton-Brown, three saccrococcygeal teratomas, one presacral ganglioneuroma one neuroblastoma and one acute lymphocytic leukemia occurred in children with confirmed NSD1 mutation." (PMID 17825104, 2007). "Hypermethylation exerted by NSD1 is also associated with poor outcomes in high-risk neuroblastoma." (PMID 31727171, 2019). "NSD1 has been implicated in cancers of the brain such as glioma and neuroblastoma and there has been extensive work done on characterization of the NSD family including crystal structures for each of NSD1 / NSD2 and NSD3." (PMID 26781748, 2016). "The histone methyltransferase gene nuclear receptor SET domain containing protein-1 (NSD1) is another example of histone modifier that is silenced by DNA hypermethylation in glioma and neuroblastoma, (a cancer of the peripheral nervous system)." (PMID 22771539, 2013). "Sotos cases with NSD1 anomalies have been reported with small cell lung cancer, ganglioglioma, neuroblastoma in two cases, and acute myelocytic leukemia." (PMID 17825104, 2007). "Additionally, NSD1 results in hypermethylation, which brings about poor prognosis in patients with neuroblastoma." (PMID 35200072, 2022). "Hypermethylation of Nsd1 causes the upregulation of Meis1 transcript and protein due to the absence of NSD1 binding to the Meis1 promoter in neuroblastoma cells." (PMID 33402862, 2020). "Within hypermethylated c-HMRs, we detected previously reported frequent DNA hypermethylation at gene promoters such as MGMT in glioblastoma, NSD1 in neuroblastoma, ESR1 in breast cancer, GSTP1 in prostate cancer and the promoter hypermethylation of RASSF1 in various cancer contexts." (PMID 28581523, 2017). "In a tissue-specific manner NSD1 exhibits both repressing as well as activating capacities as was exemplified by reduced expression of the MEIS1 oncogene in a neuroblastoma model, while increased expression was detected in transfected cells containing the NUP98–NSD1 fusion protein." (PMID 23155469, 2012). "In addition, the epigenetic inactivation of the histone methyltransferase NSD1 leads to the specifically diminished methylation of the histone lysine residues H3K36 and increases the expression of oncogene MEIS1 in human neuroblastoma and glioma." (PMID 26430963, 2015).
head and neck squamous cell carcinoma (17 papers, 2017 to 2025). A squamous cell carcinoma that arises from any of the following anatomic sites: lip and oral cavity, nasal cavity, paranasal sinuses, pharynx, larynx, and salivary glands. "Chromosome spatial architecture, identified by SpectralTAD, shows the downstream efforts of loss of NSD1 in head and neck squamous cell carcinoma (HNSCC), together with RNA-seq results." (PMID 38782890, 2024). "In the context of head and neck squamous cell carcinoma, it has been observed that there is a significant correlation between an elevated tumor stem cell index and the presence of mutations in the NSD1 gene." (PMID 39192988, 2024). "We repeatedly found mutations in the NSD1 gene in the low-methylation group of head–neck squamous cell carcinomas (HNSC) (72% versus 4%) and LUSC (55% versus 2%) suggesting a common mechanism of hypomethylation." (PMID 35134107, 2022). "Frequent mutations in the nuclear receptor binding SET domain protein 1 (NSD1) gene have been observed in head and neck squamous cell carcinomas (HNSCC)." (PMID 33588906, 2021). "Comprehensive genomic characterization of human head and neck squamous cell carcinomas (HNSCC) identified inactivating NSD1 mutations and focal homozygous deletions in up to 10% of the patients." (PMID 34575025, 2021). "A previous report also demonstrated that CRISPR-Cas9 mediated NSD1 mutations in head and neck squamous cell carcinoma lead to an improvement in the survival of patients." (PMID 31727171, 2019). "Separately, CRISPR-Cas9 mediated-NSD1 mutations in head and neck squamous cell carcinoma improve the survival of patients." (PMID 31727171, 2019). "Recent reports indicate that inactivating mutations in the histone methyltransferase NSD1 define an intrinsic subtype of head and neck squamous cell carcinoma (HNSC) that features pronounced DNA hypomethylation." (PMID 29213088, 2017). "Notably, NSD1 exerts a global chromatin effect, and its depletion is associated with DNA hypomethylation in head and neck squamous cell carcinoma (HNSCC) cells." (PMID 38539515, 2024). "Comprehensive genomic profiling of head and neck squamous cell carcinomas by The Cancer Genome Atlas (TCGA) has identified a distinct subgroup of HPV(−) cancers with inactivating mutations in the nuclear receptor-binding SET domain protein 1 (NSD1), a methyltransferase and chromatin modifier." (PMID 31321084, 2019). "Deregulation of DNA methylation induced by NSD1 silencing in head and neck squamous cell carcinoma indicates a good prognosis." (PMID 35200072, 2022). "Over the past decades, the study of NSD1 has mainly focused on its function in tumorigenesis, including in head and neck squamous cell carcinomas, laryngeal tumors, myelodysplastic syndromes, and so on." (PMID 34099628, 2021). "We demonstrated the effectiveness of this tool through simulated datasets and a case study assessing H3K36me2 depletion following NSD1 knockout in head and neck squamous cell carcinoma, highlighting the advantages of ChIPbinner in detecting broad histone mark changes over existing software." (PMID 40128719, 2025). "Moreover, for head and neck squamous cell carcinoma, NSD1 knockdown promotes the apoptosis of inflammation cytokines and leads to the deregulation of DNA methylation." (PMID 35200072, 2022). "Inactivating mutations in NSD1 are associated with genomic hypomethylation and improved survival in head and neck squamous cell carcinoma, though no such link has been reported between NSD1 and survival in endometrial cancer." (PMID 32894083, 2020). "Inactivating NSD1 deregulates DNA methylation in head and neck squamous cell carcinoma." (PMID 31727171, 2019).
overgrowth syndrome (17 papers, 2007 to 2025). A group of syndromes caused by genetic birth defects that may lead to the development of malignancies. "Loss-of-function mutations in DNMT3A, a DNA methyltransferase, or NSD1, a histone methyltransferase, cause overgrowth syndromes." (PMID 41456056, 2025). "In humans, NSD1 variations are associated with overgrowth syndromes, with macrocephaly, and to the evolution of modern human brains and skull shape." (PMID 36550402, 2022). "This was consistent with these diseases being distinct, although extensive overlap of clinical signs between SETD2-associated phenotypes and other overgrowth syndromes related to NSD1, EZH2 or DNMT3A in Sotos, Weaver and Tatton-Brown-Rahman syndromes, respectively, has been reported." (PMID 33916664, 2021). "Nine patients out of 239, referred as overgrowth syndrome, were analyzed through NGS, which resulted in carrying a mutation in a different gene than NSD1." (PMID 36833222, 2023). "The fact that the NSD1+/−-specific signature allows the molecular distinction of two clinically overlapping overgrowth syndromes provides further evidence for the robust specificity of the NSD1+/−-specific signature." (PMID 26690673, 2015). "Interestingly, a study conducted on an overgrowth syndrome characterized by NSD1 deficiency, a molecular defect found in a subset of BWS, demonstrated the role of NSD1 as a specific co-activator for a novel enhancer in DMR0 affecting IGF2-p0 transcriptional activity in a cell-type-specific manner." (PMID 37371750, 2023). "However, no deletions were identified in 78 overgrowth syndrome cases without NSD1-mutation." (PMID 27834868, 2016).
breast carcinoma (12 papers, 2015 to 2025). "In paclitaxel-resistant MCF7 breast cancer cells, NSD1 knockdown inhibits EMT, migration and invasion, while restoring sensitivity to paclitaxel." (PMID 41301842, 2025). "NSD1 is upregulated in paclitaxel-resistant MCF7 breast cancer cells, and its knockdown in these cells attenuates cell growth and induces apoptosis." (PMID 41301842, 2025). "Then, they investigated the role of NSD1 in paclitaxel-mediated drug resistance using parental MCF-7 (ER + breast cancer) versus MCF-7 PR (paclitaxel-resistant) cell lines." (PMID 36814601, 2023). "NSD1 reportedly facilitates the epithelial-mesenchymal transition, migration, and invasion of paclitaxel-resistant breast cancer cells by regulating NF-κB." (PMID 37176149, 2023). "We found that copy number amp/gain of NSD1 or PRDM1, or loss of SETDB2 or PRDM10 was significantly associated (p<0.05) with shorter survival in breast cancer patients." (PMID 25537518, 2015). "Two of them, PATL1 and PRRC2B were discussed earlier; SENP7 is a marker of poor prognosis in colon cancer; SPAG9 is expressed in a variety of malignancies and regulated by QKI in lung cancer; UBR5 promotes postsurgical breast cancer lung metastases, and NSD1 exerts tumor suppressive functions." (PMID 39664813, 2024). "The authors identified a positive correlation between WNT10B and NSD1 in breast cancer tissue." (PMID 36814601, 2023). "One percent of breast cancers showed NSD1 alterations (n=482)." (PMID 25611383, 2015). "However, the function and mechanism of NSD1 in paclitaxel-resistant breast cancer remain obscure." (PMID 34905470, 2021). "Xenograft models further support the tumor-promoting function of NSD1 in both HCC and breast cancer." (PMID 41301842, 2025). "NSD1 c.3056G>A (p.R1019H) was found in a woman diagnosed with breast cancer and 20 colon adenomas at age 50, and with no family history of cancer." (PMID 35158968, 2022).
developmental delay (12 papers, 2015 to 2025). "The third Sotos patient DGDP291 with a novel NSD1 mutation also shows a typical Sotos phenotype including post-natal overgrowth, developmental delay and facial gestalt." (PMID 27834868, 2016). "Interestingly, patients with NSD1 duplication have reciprocal phenotypes such as microcephaly and developmental delay, indicating that NSD1 is highly associated with brain development." (PMID 32660023, 2020). "This enrichment in neural and cellular development pathways reflects the cardinal features of SS (that is, overgrowth and developmental delay) and validates the utility of the DNAm signature to elucidate the functional, biological and molecular impact of NSD1 pathogenic variants." (PMID 26690673, 2015). "In contrast, duplication of NSD1 in the microduplication 5q35 syndrome leads to microcephaly in 74% of cases, with undergrowth, and developmental delay in close to 90% of the cases." (PMID 36845425, 2023). "Overexpression of NSD in Drosophila recapitulates the phenotypes of human NSD1 duplication disease, such as developmental delay, and induces apoptosis through a JNK signaling pathway." (PMID 32660023, 2020). "Interestingly, duplication of NSD1 results in microcephaly in 74% of 5q35 syndrome cases, along with growth restriction and developmental delay in nearly 90% of affected individuals." (PMID 40469903, 2025). "It is reported that NSD1 is an important gene for early post-implantation and embryonic development, aligning with its involvement in a congenital disease characterized by developmental delay and overgrowth." (PMID 39336709, 2024).
hepatocellular carcinoma (11 papers, 2019 to 2025). A malignant tumor that arises from hepatocytes. "NSD1 is overexpressed in hepatocellular carcinoma (HCC) and breast tumor tissues and correlates with poor prognosis." (PMID 41301842, 2025). "They performed quantitative real-time polymerase chain reaction (RT-qPCR) and western blot analysis to pinpoint the expression of NSD1 in tissue affected in hepatocellular carcinoma." (PMID 38186450, 2023). "NSD1 promotes the progression of acute myeloid leukemia, multiple myeloma, and lung cancer, as well as cancer cell migration and invasion in hepatocellular carcinoma (HCC), pediatric glioma, and breast cancer." (PMID 35581654, 2022). "NSD1 has been reported to serve as a regulator for various cancers, such as head and neck cancer, pancreatic cancer, and hepatocellular cancer." (PMID 35200072, 2022). "As reported, NSD1 inhibits H3K27me3 methylation to promote Wnt10b transcription in the development of hepatocellular carcinoma." (PMID 34905470, 2021). "WNT10B is also regulated by NSD1 in hepatocellular carcinoma (see Section 17.14)." (PMID 36814601, 2023). "Moreover, NSD1 gene-silencing inhibits the proliferative, migratory and invasive abilities of hepatocellular carcinoma cells." (PMID 35888078, 2022). "Moreover, NSD1 is reported to regulate hepatocellular carcinoma progression through the Wnt/β-catenin signaling pathway." (PMID 35200072, 2022). "The high NSD1 expression in hepatocellular carcinoma promotes cellular processes." (PMID 35200072, 2022). "Additionally, NSD1 knockout is reported to inhibit the proliferative, migratory, and invasive abilities of hepatocellular carcinoma cells." (PMID 34905470, 2021). "The nuclear receptor binding SET domain-containing protein 1 (NSD1) was one of the biomarkers to participate in a variety of malignancies, and human hepatocellular carcinoma (HCC) was one of them." (PMID 35935840, 2022).
lung carcinoma (11 papers, 2010 to 2024). "For example, lung cancer stem cells carry loss-of-function mutations in nuclear receptor-binding SET domain protein 1 (NSD1), which is capable of methylation-modifying histones." (PMID 37144123, 2023). "Inactivating NSD1 mutations have also been described in several other malignancies, including lung cancer, clear cell renal carcinoma, and skin cancer, suggesting a role of NSD1 as a tumor suppressor." (PMID 31321084, 2019). "Overexpression and mutations of the three NSD family members (NSD1, NSD2, and NSD3) have been linked to several types of cancers, including lung cancer, breast cancer, prostate cancer, acute myeloid leukaemia, acute lymphoblastic leukaemia, and multiple myeloma." (PMID 37667522, 2023). "Some newly uncovered aberrations contained oncogenes such as FUS at 16p11.2 and NSD1 at 5q35.2–q35.3, whose association with lung cancer has hitherto not been reported." (PMID 21151896, 2010).
Intellectual disability (9 papers, 2012 to 2025). "Dominant NSD1 (Nuclear receptor-binding Set Domain protein 1) mutations account for about 60% of SOTOS1 cases; very rarely, patients with Sotos clinical features and pUPD11, or cases with NSD1 mutations and clinical diagnosis of BWS with additional intellectual disability, have been reported." (PMID 33810554, 2021). "It has been suggested that this lack of family cases could be related to the presence of intellectual disability and a underlying defect in fertility associated with NSD1 mutations, which can affect the possibility of having offspring." (PMID 36833222, 2023).
microcephaly (8 papers, 2013 to 2025). A congenital or acquired developmental disorder in which the circumference of the head is smaller than normal for the person's age and sex. "Several clinical studies on NSD1 suggest that the microcephaly associated with NSD1 increased dosage appears to be postnatal." (PMID 36845425, 2023). "A duplication of the distal arm of chromosome 5q is known to be associated with short stature and microcephaly, and an increased dosage of NSD1 gene was proposed to be responsible for a combination of these two features." (PMID 23342975, 2013). "Therefore, differences in NSD1 gene dosage that elicit gain or loss of function phenotypes result in either microcephaly or macrocephaly, respectively." (PMID 36845425, 2023). "For example, whereas NSD1 haploinsufficiency is associated with overgrowth, reciprocal duplications involving NSD1 correlate with opposing clinical features, including growth retardation, delayed bone age and microcephaly." (PMID 31575610, 2019). "In addition to the potential role of ASH1L in the control of brain size postnatally, clinical studies suggest that mutations in either NSD1, NSD2, SETD2, or SETD5 have also been implicated in microcephaly." (PMID 36845425, 2023). "Interestingly, NSD overexpression in glial cells, not neurons, induces brain cell death, behavioral defects, and a decrease in brain size that is similar to the microcephaly phenotype of patients with NSD1 duplication." (PMID 32660023, 2020). "Similarly, to NSD1, ASPM (abnormal spindle-like, microcephaly-associated; MCPH5) undergoes positive selection in selected exons throughout the primate lineage leading to humans and currently is associated to microcephaly." (PMID 36550402, 2022). "Nonetheless, our patient had a duplication encompassing NSD1 but although short statured, he did not presented with a microcephaly." (PMID 23342975, 2013).
head and neck cancer (7 papers, 2019 to 2024). A primary or metastatic malignant neoplasm affecting the head and neck. "NSD1 mutations are observed in head and neck cancer and are associated with increased PDL1 expression." (PMID 36048239, 2022). "It was suggested that the head and neck cancer patients with mutations in NSD1 have an improved prognosis and high level of NSD1 renders the resistance of head and neck cancer cells to chemotherapy." (PMID 34905470, 2021). "Loss-of-function mutations in NSD1 are associated with global genome hypomethylation in head and neck cancer." (PMID 31321084, 2019). "As for the distinct subgroup within HPV(−) head and neck cancers with inactivating NSD1 mutations, the clinical implications of this genetic alteration have yet to be fully explored." (PMID 31321084, 2019). "NSD1 inhibition has been shown to enhance sensitivity to cisplatin and carboplatin in head and neck cancer cell lines, but the impact of loss-of-function mutations in NSD1 on cetuximab response is unknown." (PMID 31914141, 2020). "Genetic alterations in NSD1 hold potential as novel prognostic biomarkers in HPV(−) head and neck cancers." (PMID 31321084, 2019). "This study identified the PIP4K2B protein as a key target of NSD1 in head and neck cancer." (PMID 38539515, 2024). "Knockdown of NSD1 in head and neck cancer cells resulted in decreased expression of CCL5 and suppressed T-cell infiltration into the tumor microenvironment, suggesting that NSD1 inactivation in cancer has implications for cancer immunotherapy." (PMID 36048239, 2022). "Although the database did not include enough head and neck cancer cell lines for separate cohort analysis, the pan-cancer cohort showed significantly increased sensitivity (p = 0.0198) to cisplatin for cell lines with NSD1 mutations (n = 18) compared to those with wild-type NSD1 (n = 798)." (PMID 31321084, 2019). "Since PIP4K2B affects PI3K and mTORC1 signaling, and as we recently showed that NSD1 depletion decreases Akt/mTORC1 signaling, we investigated whether mTORC1 regulation could be PIP4K2B-dependent in head and neck cancer." (PMID 38539515, 2024). "However, no studies have examined the differences of NSD1 mutations between HPV-positive and HPV-negative head and neck cancers." (PMID 31321084, 2019). "However, in contrast to HPV(−) tumors, mutant NSD1 was not underexpressed in our limited set (n = 6) of HPV(+) head and neck cancer specimens, though this finding must be examined in a larger cohort before any definitive conclusions can be drawn." (PMID 31321084, 2019).